KRTAP10-6 (keratin associated protein 10-6)
Description:
In the hair cortex, hair keratin intermediate filaments are embedded in an interfilamentous matrix, consisting of hair keratin-associated proteins (KRTAP), which are essential for the formation of a rigid and resistant hair shaft through their extensive disulfide bond cross-linking with abundant cysteine residues of hair keratins. The matrix proteins include the high-sulfur and high-glycine-tyrosine keratins.
Synonyms: KAP10.6; KRTAP18-6; KRTAP18.6; KAP18.6
Tractability: No criterion of Open Targets' tractability assessment is met for any kind of drug.
Gene: Protein-coding gene on chromosome 21 (44,591,268 to 44,592,505, reverse strand). Ensembl gene ENSG00000188155.
Pathways (Reactome):
Developmental Biology: Keratinization
Gene Ontology:
Molecular function: protein binding
Cellular component: cytosol; keratin filament
Genetic constraint (gnomAD): Loss-of-function variants: 1 observed, 1.13 expected, observed/expected ratio (o/e) 0.89, 90% interval 0.25 to 1.88. That is too few expected variants to judge how well the gene tolerates losing a copy. Missense variants: 335 observed, 404.81 expected, observed/expected ratio (o/e) 0.83, 90% interval 0.76 to 0.91. Synonymous variants: 136 observed, 155.51 expected, observed/expected ratio (o/e) 0.87, 90% interval 0.76 to 1.01.
Homologues: Orthologues: macaque KRTAP10-9 (64% identical), rat Krtap10-9 (50% identical), rat LOC120098854 (47% identical), rat Krtap10-1 (46% identical), mouse Krtap10-32 (45% identical), mouse Krtap10-33 (44% identical), rat Krtap10-1l1 (44% identical), mouse Krtap10-30 (41% identical), mouse Krtap10-34 (41% identical), mouse Krtap10-21 (40% identical), mouse Krtap10-23 (40% identical), mouse Krtap10-25 (40% identical), and 25 more. Paralogues in human: KRTAP10-7 (70% identical), KRTAP10-4 (65% identical), KRTAP10-11 (65% identical), KRTAP10-9 (65% identical), KRTAP10-5 (57% identical), KRTAP10-10 (55% identical), KRTAP10-2 (55% identical), KRTAP10-12 (54% identical), KRTAP10-1 (53% identical), KRTAP10-3 (47% identical), KRTAP10-8 (47% identical), KRTAP16-1 (28% identical), and 35 more.